MTOR (mechanistic target of rapamycin kinase)
Diseases named in the same sentence as MTOR in open-access papers (continued):
Sharing a sentence is not in itself a finding about the gene and the disease.
cancer (continued). "In this study, low concentrations of everolimus in vitro (1, 10, and 100 nM), when used as a single treatment agent, were sufficient to potently inhibit mTOR signaling and cancer cell viability in vitro." (PMID 28793923, 2017). "Previous studies indicated that miR-199a-3p is an inhibitor of mTOR, and miR-199a-3p plays a role as a tumor suppressor by targeting mTOR in several cancers." (PMID 28422725, 2017). "Similar approaches using metformin, which also inhibits mTOR pathway signaling are also being tested in preclinical and clinical studies to favorably reprogram metabolism and prevent cancer." (PMID 28959684, 2017). "Here, we report that mitochondrial AKAP1 is a novel transcriptional target of Myc which controls the mTOR pathway and cancer cell growth." (PMID 28569781, 2017). "Widespread activation of the PI3K/Akt/mTOR pathway in human cancer has made it an attractive target for therapeutic inhibition." (PMID 28445155, 2017). "Evidence indicates that the inhibition of the PI3K/Akt/mTOR pathway primes cancer cells for mitochondrial apoptosis by tipping the balance toward antiapoptotic Bcl-2 proteins, resulting in increased mitochondrial outer membrane permeabilization." (PMID 28959140, 2017). "The place of mTOR inhibitors in cancer needs, therefore, to be reconsidered, and novel therapeutic strategies based on mTOR inhibition have to be established." (PMID 29104248, 2017). "When bound by ligands like neuregulin, ERBB4 activates numerous downstream pathways, including Ras/MAPK/ERK and PI3K/AKT signaling (via mTOR), to regulate both normal cellular processes and cancer development and progression." (PMID 28042953, 2017). "Nonetheless, recent studies have demonstrated that pharmacologic inhibition of PI3K/AKT/mTOR signaling with rapamycin and its analogues is a potent cancer-selective therapeutic strategy for many tumor types." (PMID 29340076, 2017). "The PI3K-Akt-mTOR pathway is one of the principal proliferative pathways and often up-regulated in human cancer." (PMID 28542590, 2017). "MTOR plays an important role in cell differentiation and growth, cellular metabolism and cancer metabolism." (PMID 28754963, 2017). "PI3K, Akt and mTOR play significant roles in metabolism and their deregulation can lead to different cancers." (PMID 28659828, 2017). "One possible explanation was that the follow-up period in our cohort was too short to show the effectiveness of mTOR inhibitors in the prevention of cancer recurrence." (PMID 28160552, 2017). "Thus, the use of precise molecular therapeutic approaches to reduce the activity of the mTOR pathway could have anti-cancer effects in HNSCC, and the dissection of the underlying mechanisms may help select the patient population that will benefit the most from this therapy." (PMID 28822012, 2017). "As illustrated in the results section, three interconnected proteins, ARFGEF1, PLD2, and RPTOR, were successively activated, stimulating the cancer driver mTOR SP." (PMID 29062084, 2017). "mTOR lies at the hub of intracellular and extracellular signal transduction pathways and the mTOR kinase-mediated signaling is deregulated in most cancers." (PMID 28507282, 2017). "PI3K/AKT/mTOR pathway inhibition can also sensitize cancer cells to chemotherapy, providing a rationale for BKM120 and chemotherapy combinations." (PMID 28662162, 2017). "Our objective was to evaluate relationships between mTOR-pathway activity and functional mutations in the upstream genes PIK3CA and PTEN in solid-tumor biopsies from a broad selection of cancer types." (PMID 29137436, 2017). "Up to now, therapeutic approaches for STK11 mutant cancer were mainly conducted through the restoration of the mTOR pathway using mTOR inhibitors or phenformin, an analog of metformin, without taking into account the potential dual effect of STK11 mutations." (PMID 26625312, 2017).
cancer (continued). "One of the most common events in human cancer is hyperactivation of the phosphatidylinositol-3-kinase (PI3K)/AKT/mammalian target of rapamycin (mTOR) signaling pathway, generally described as a consequence of genetic alterations of pathway members." (PMID 29404273, 2017). "Up-regulated mTOR signaling is involved in the development, progression and metastasis of many different cancers including colorectal, prostate and breast cancer." (PMID 28966806, 2017). "Up-regulation of the PI3K/Akt/mTOR pathway has been documented in many cancers, including OC, and inhibition of this pathway is thought to be a promising therapeutic target for cancer treatment." (PMID 29340030, 2017). "The PI3K/AKT/mTOR signaling pathway is also known to be overstimulated in cancer cells or in tumors resistant to treatments such as chemotherapy, radiation, as well as hormone therapy." (PMID 28978144, 2017). "They found that inhibition of PI3K, AKT, or mTOR decreased PD-L1 expression in EGFR-mutated NSCLC cell lines, which was similar to our finding in HER2-amplified cancer cell lines." (PMID 28969039, 2017). "Gain-of-function-mutations in the mTOR FAT domain cause hyperactivation, leading to increased proliferation of cancer cells and poor prognostic outcomes for patients." (PMID 29084988, 2017). "The phosphatidylinositol-3-kinase (PI3K)-protein kinase B (Akt)-mTOR pathway is one of the most important autophagy signalling pathways in cancer growth and progression." (PMID 28320471, 2017). "Inhibition of the mTOR pathways is consequently one of the targeted areas for development of anti-cancer agents." (PMID 28464864, 2017). "Further investigation using other genomic candidates and new-generation mTOR inhibitors is warranted in patients with treatment-refractory cancer." (PMID 28330462, 2017). "mTOR has been shown to regulate glycolysis and mTOR inhibitors have been shown to suppress glycolysis of various cancers." (PMID 29262588, 2017). "The mammalian Target of Rapamycin (mTOR) is a negative regulator of autophagy in cancer cells and its phosphorylation mTOR is inhibited by curcumin and related compounds." (PMID 28238104, 2017). "In cancer, glutamine also sustains proliferative signaling via mammalian target of rapamycin (mTOR) activation and enables replicative immortality by suppressing senescence and resisting cell death." (PMID 28553292, 2017). "The complexities of GSK-3β function and interactions with PI3K/AKT/mTOR signaling, cell cycling, and apoptotic pathways are poorly understood in the context of lymphomagenesis and cancer therapeutics." (PMID 29383130, 2017). "Anti-cancer activity of Sirolimus and other mTOR inhibitors have been explored in many cancers but very little is known in CPC." (PMID 28993730, 2017). "Currently, numerous mTOR inhibitors (rapamycin or rapamycin analogues) are being developed and many are tried in the clinics for the cancer patients." (PMID 28831205, 2017). "Targeting the PI3K/AKT/mTOR pathway has been proposed as a clinical strategy to eliminate cancer stem cells." (PMID 28915623, 2017). "Our findings suggest the possibility of a new anti-cancer treatment strategy using ERBB4-Akt/mTOR inhibitors in CSCNET patients." (PMID 28042953, 2017). "Unregulated activation of the PI3K/Akt/mTOR pathway is a prominent feature of many human cancers and PI3K is activated or over-expressed in all major cancers." (PMID 27769061, 2017). "Specifically for cancer pathogenesis, many studies have documented the important role of mTOR pathway." (PMID 28822012, 2017). "Several studies suggest PI3K/Akt/mTOR signaling to be a critical pathway that negatively regulates autophagy and promotes cancer progression and is known to be upregulated in 30–50% of PCa." (PMID 28678839, 2017). "Collectively, these data disclose a previously unrecognized role of AKAP1 in mTOR pathway regulation and cancer growth." (PMID 28569781, 2017).
cancer (continued). "mTOR signaling pathway plays a critical role in cancer progression, resistance to chemotherapy and poor prognosis by modulating the activation of many target genes." (PMID 28406985, 2017). "Abnormal activation of the PI3K/Akt/mTOR pathway has been found in various cancers and has been suggested to stimulate proliferation and drug resistance." (PMID 28977849, 2017). "Comprehensive expression profiling of p-mTOR in human tissues would provide an insight into diverse roles of this molecule in normal and cancer tissues." (PMID 28831205, 2017). "In fact, our study has already recruited the largest number of kidney transplant recipients who had mTOR inhibitor conversion due to post-transplant cancers." (PMID 28160552, 2017). "Earlier studies found that inhibition of the PI3K/Akt/mTOR signaling pathway reversed resistance in several types of cancer." (PMID 28977849, 2017). "Although prior studies observed radiosensitization in response to treatment with dual PI3K/mTOR inhibitors (in other cancer cell lines both in vitro and in vivo), an in vitro condition does not truly represent clinical scenarios." (PMID 28978144, 2017). "The PI3K/Akt/mTOR pathway is a fundamental survival signaling constitutively activated in many types of cancer." (PMID 29228561, 2017). "Through the analysis of these resistant cells, we identified the mTOR pathway, an important proliferation factor in various cancers including CRC, as a crucial resistant factor to tankyrase inhibitors." (PMID 28615517, 2017). "Overexpression of molecules of the PI3K/Akt/mTOR signaling pathway are found in many types of human cancers, and proved to activate cell growth and tumorigenesis." (PMID 27992366, 2017). "The PI3K/Akt/mTOR pathway is activated in many types of cancers and has been demonstrated to contribute to treatment resistance." (PMID 28108737, 2017). "Inhibitors of mTOR, such as miRNAs, can inhibit tumor cell growth in many cancers by blocking the AKT/mTOR signaling pathway." (PMID 28422725, 2017). "Dysregulation of the mTOR pathway occurs in many human diseases, especially certain cancers such as breast cancer, where it is a known therapeutic target." (PMID 28504970, 2017). "AMPK signaling exerts regulatory effects on cancer cell adhesion, migration and invasion, which is involved in different mechanisms including disruption of the mTOR, TGF-b, Pdlim5, CXCL12, NF-κB and Akt-MDM2-Foxo3a pathways." (PMID 29245964, 2017). "Through the mTOR inhibition, metformin arrests cell cycle and cell growth, because mTOR is a downstream effector of PI3K/AKT pathway, a signaling pathway linked to cancer cell growth and proliferation." (PMID 29075616, 2017). "Accordingly, the suppression of the class I PI3K/Akt/mTOR pathway is an imperious and attractive target for cancer therapy." (PMID 29245957, 2017). "Many studies have indicated that the PI3K/Akt/mTOR pathway is involved in cell proliferation and apoptosis in various cancer cells." (PMID 28545465, 2017). "PTEN, a well-known tumor suppressor that is competitively regulated by GAS5 in the subpathway region, inhibits the cancer-related IGF-1/mTOR pathway." (PMID 28152521, 2017). "It has been reported that NF-κB is regulated by the upstream signaling of Akt and Akt/mTOR in cancers." (PMID 29156828, 2017). "The prognostic significance of p-mTOR expression has been explored extensively in many types of cancer; however, the results remain controversial." (PMID 28114374, 2017). "MTOR (mechanistic target of rapamycin) is another serine/threonine protein kinase that promotes cellular growth and is also often targeted in cancer therapy." (PMID 28102733, 2017).
cancer (continued). "The anti-cancer activity by the first generation of mTOR inhibitors, or rapalogs, is generally limited, as they only block mTORC1, but not mTORC2." (PMID 28404914, 2017). "Naringin was found to induce autophagic growth inhibition via downregulation the PI3K/Akt/mTOR cascade in concurrence with activation of MAPK pathways in AGS cancer cells." (PMID 28675698, 2017). "Phosphorylated mammalian target of rapamycin (p-mTOR) is a promising prognostic marker in many types of cancer." (PMID 28114374, 2017). "Previous studies have implicated mutations or altered expression in individual enzymes, or alterations in specific signalling pathways (e.g., PI3K, AKT or mTOR) in driving the metabolic adaptations observed in a variety of cancers." (PMID 28163917, 2017). "Pathways in cancer, mTOR signaling, oxidative phosphorylation, cell cycle, apoptosis, and DNA replication were significantly enriched KEGG pathways." (PMID 28477009, 2017). "A master promoter of cell growth, mammalian target of rapamycin (mTOR) is upregulated in a large percentage of cancer cells." (PMID 28616576, 2017). "It has been reported that mTOR pathway regulates the transcription, translation and stability of Cyclin D1 in various types of cancer cells." (PMID 28743911, 2017). "Mammalian target of rapamycin (mTOR) signaling represents an important regulator of cellular proliferation in cancer." (PMID 29057925, 2017). "Overall, mTOR-pathway activation was identified in 444/538 (83%) samples representing 40 different cancer types." (PMID 29137436, 2017). "One of the widely studied mechanisms for cancer cell resistance to IGF-IR inhibition is the upregulation of AKT/mTOR signaling pathway." (PMID 27661006, 2017). "Many drugs such as Sirolimus, Torin1 and PP242 have also been developed to target mTOR, as well as its downstream pathway, with the aim of targeting various cancers, diabetes, neurodegenerative diseases and aging." (PMID 28968999, 2017). "Novel protein interactions with AKT/mTOR pathway members have been commonly reported to efficiently regulate AKT1 kinase activity in cancers." (PMID 28978011, 2017). "AMPK is a possible therapeutic target for cancers with activated Akt signaling because AMPK inhibits mTOR, which is downstream of Akt." (PMID 28052030, 2017). "Particularly, 320-IWR cells overexpressed prominin 1 (CD133), a well-known marker of cancer stem cells, and mTOR activation was also reported in cancer stem cells." (PMID 28615517, 2017). "The serine/threonine kinase mTOR has become a striking therapeutic target for the treatment of cancer and various studies revealed that mTOR kinase negatively regulates autophagy." (PMID 29029506, 2017). "PTEN deficiency induces tumor progression or invasion via different pathways, including the PI3K/AKT/mTOR pathway, in various cancers." (PMID 29228674, 2017). "Pathways in cancer, mTOR signaling and oxidative phosphorylation were significantly enriched in the KEGG pathway analysis of dysregulated mRNAs identified in the PBMCs of patients with SCO compared to healthy individuals." (PMID 28477009, 2017). "Compounds that target PI3K/PTEN/Akt/mTOR signaling are of considerable interest as anti-cancer agents, and several have been studied in clinical trials." (PMID 29312623, 2017). "The phosphoinositide 3-kinase (PI3K)-v akt murine thymoma viral oncogene homolog (AKT)-mechanistic target of rapamycin (mTOR) signaling cascade is one of the most important intracellular pathways that is frequently activated in diverse cancers." (PMID 28330462, 2017). "mTOR inhibitors have demonstrated remarkable anti-tumor activity in experimental models, mainly by reducing cancer cell growth and tumor angiogenesis." (PMID 29104248, 2017).
cancer (continued). "The mTOR pathway is often activated in various cancers including CRC and plays a critical role in tumor growth." (PMID 28615517, 2017). "Since activation of mTOR is important for cancer cell proliferation, the activity of CZ415 on OS cell proliferation was tested next." (PMID 29137241, 2017). "Overall, the biological effect of metformin on cancer cells is based on its ability to activate AMPK or inhibit downstream growth factor signaling through inhibition of mTOR." (PMID 28126011, 2017). "Further, it confirms that strategies to beat cancer based on targeted monotherapies, at least in the case of mTOR, will probably require further reconsideration to mitigate those adverse consequences." (PMID 28616576, 2017). "Scientists in this study demonstrated that the mechanism of anti-cancer role was through PI3K/Akt/mTOR signaling pathway." (PMID 29179444, 2017). "Based on the frequent upregulation of the PI3K/AKT/mTOR pathway in human cancer, and its role in driving tumour cell growth, several inhibitors have been developed which target either the mTORC1 complex or mTOR directly." (PMID 28544747, 2017). "As genetic alterations in PI3K/AKT/mTOR signaling have been recognized as pivotal cancer drivers, considerable efforts have been employed to generate a plethora of inhibitors for such pathway components." (PMID 28353628, 2017). "PD-L1 plays as an immune checkpoint inhibitor, which is highly expressed in many types of cells, including cancer cells, and its levels can be inhibited by a mTOR pathway inhibitor, rapamycin." (PMID 29212184, 2017). "The PI3K/AKT/mTOR signaling pathway has been extensively studied owing to growing evidence supporting its critical role in cancer progression; it influences metabolism, tumor growth, survival, and the development of metastases." (PMID 28978144, 2017). "The positive regulation of mTOR by PI3K/Akt signaling pathway was found to be involved in the pathogenesis of cancer." (PMID 28659990, 2017). "The RAS/MAPK/ERK and AKT/mTOR signal pathway has been verified to play critical roles in the development and progression of human carcinomas." (PMID 28280729, 2017). "In the present study, an immunohistochemical analysis of the expression pattern of phosphorylated mTOR (p-mTOR) was performed in human normal fetal and adult tissues and various carcinoma tissues." (PMID 28831205, 2017). "PLC-γ1 is known to play a role in the progression of several carcinomas by activating PI3K/AKT/mTOR and MAPK pathways which regulate cell proliferation and survival." (PMID 28978037, 2017). "In the present study, an immunohistochemical analysis was performed to explore the expression pattern of p-mTOR in human normal fetal and adult tissues and various carcinoma tissues." (PMID 28831205, 2017). "While examining the role of mTOR in cancer, rapamycin-insensitive mTORC2 complex was discovered and is now being targeted by second generation dual inhibitors such as MLN0128 that directly phosphorylates Akt at S473." (PMID 26536665, 2016). "Available data on the role and activation status of the PI3K/Akt/mTOR pathway in cancer patients is very limited." (PMID 26856534, 2016). "As noted, it is very common that cellular signaling pathways involving the mTOR complexes are abnormally upregulated in cancer." (PMID 27635236, 2016). "Not only macrophages but also cancer cells present mTOR pathway activation that modulates different molecules that contribute to the tumoral microenvironment." (PMID 28074082, 2016). "The mechanistic target of rapamycin (mTOR) is a major regulator of cell growth and is frequently dysregulated in cancer." (PMID 27015560, 2016). "Wide-ranging researches have indicated that miRNAs-based regulation of the mTOR pathway plays a key role in cancer progression, and this pathway is a promising target by miRNAs for novel anticancer therapies." (PMID 27540517, 2016).